INS (insulin)
Diseases named in the same sentence as INS in open-access papers (continued):
Sharing a sentence is not in itself a finding about the gene and the disease.
insulinoma (continued). "Indeed, BACE1−/− mice show impaired insulin expression in the pancreas and siRNA-mediated BACE1 knockdown significantly reduces insulin mRNA and protein in insulinoma cells." (PMID 32728795, 2020). "The stronger staining of SPY than CgA in insulinomas may also implicate robust SPY participation in insulin secretion through endocytosis." (PMID 32020844, 2020). "In the pancreatic islet cells adenoma (insulinoma), insulin secretion is dysregulated with a persistent hypersecretion that may lead to severe hypoglycemia with associated-neuroglycopenic symptoms." (PMID 32664294, 2020). "Positive or scattered insulin expression was observed in all insulinomas." (PMID 32103422, 2020). "High levels of insulin and proinsulin are common in the patients with insulinomas." (PMID 32124259, 2020). "In contrast, amended insulin-glucose ratios had sensitivity and specificity of 98% in insulinoma." (PMID 33679602, 2020). "Analogously, the only abnormal cell type that produces insulin is the insulinoma cell." (PMID 33060578, 2020). "In normal mouse pancreatic islets, α-cells are located on the periphery of the islet secrete glucagon, whereas β-cells are located at the centre of the islet secrete insulin, and hence, it would be expected that glucagonomas would arise from α-cells and insulinomas from β-cells." (PMID 32348957, 2020). "This suggests that NFATC1 may serve as an alternate driver of INS/IGF2 expression in insulinomas, possibly facilitated by looping from the SYT8/TNNI2 locus." (PMID 33060578, 2020). "Furthermore, pancreatic-β-cell-specific IRE1α-conditional KO (cKO) mice and IRE1α-cKO insulinoma cell lines showed the requirement of IRE1α for the upregulation of insulin-folding enzymes to balance with insulin requirements." (PMID 32397116, 2020). "Furthermore miR-204 is primarily expressed in insulinomas and correlates with insulin expression on tissue." (PMID 32537434, 2020). "Transdifferentiation of ARX-positive PNENs to insulin-producing PNENs could provide an explanation for these observations and the more malignant behavior of these exceptional insulinomas." (PMID 32512761, 2020). "Rat insulinoma INS-1 cells are widely used to study insulin secretory mechanisms." (PMID 33240888, 2020). "Indeed, the GLP-1R is also overexpressed in insulin-producing islet cell tumors, that is, insulinomas." (PMID 31951592, 2020). "We think that insulinoma, as a “natural” model of endogenous oversecretion of insulin, could be used to evaluate the effect of insulin and proinsulin on circulating levels of ghrelin in the patients." (PMID 32124259, 2020). "Indeed, micromolar ABA stimulated insulin release in vitro, from rat insulinoma cells and from isolated human islets, and also in vivo, in the perfused rat pancreas." (PMID 32526875, 2020). "The positive relationship between PET and MRI signals suggests that an increase in the β-cell mass in insulinomas could also be related to a respective increase of β-cell function and, thus, to the capacity of the pancreas to secrete insulin." (PMID 31903128, 2020). "Moreover, downregulation of Park2 in rat insulinoma INS-1 β cells caused significant reduction in intracellular ATP level, GSIS, and intracellular insulin expression." (PMID 32653024, 2020). "The insulin gradient indicated the tail of the pancreas as the site with the lowest probability to host the insulinoma and a decision to resect the pancreatic neck was made, as a deviation from current recommendation, because of the suggestive very high insulin release from that region." (PMID 32047477, 2020). "Again, the use of cell lines instead of isolated pancreatic islets is an important limitation, although INS1 rat insulinoma cells are recognized models for rat β-cells, because they retain major mechanisms of insulin secretion regulation, including the responsiveness to high versus low glucose." (PMID 32650579, 2020).
insulinoma (continued). "Impaired counterregulatory response to hypoglycemia in patients with TS may result in symptomatic hypoglycemia with only mild insulin elevation and elevated proinsulin in setting of hypoglycemia may be the only indication of insulinoma in these patients." (PMID 30881705, 2019). "In addition, the elevation of insulin in the patients with insulinoma was significantly higher than in the patients with islet hyperplasia." (PMID 31743337, 2019). "Insulinoma is a functional tumor of the pancreas that can secrete insulin autonomously." (PMID 31743337, 2019). "Monitoring of the insulin/glucose ratio during surgery may be helpful in assessing successful insulinoma excision." (PMID 31263451, 2019). "If these studies fail to localize the insulinoma(s), more invasive techniques such as selective angiography with intra-arterial calcium stimulation and hepatic venous sampling for insulin levels may localize more than 80% of these neoplasms." (PMID 31263451, 2019). "ERα enhances insulin synthesis in cultured insulinoma (INS-1) cells." (PMID 30790128, 2019). "Overexpressing GPLD1 in an insulinoma cell line enhanced glucose-stimulated insulin secretion." (PMID 31369641, 2019). "The clinical presentation can be due to symptoms related to hormone over-secretion by the tumor, such as excess insulin (insulinoma), gastrin (gastrinoma), glucagon (glucagonoma), vasoactive intestinal peptide (VIPoma), somatostatin (somatostatinoma), or pancreatic polypeptide (PPoma)." (PMID 31207914, 2019). "Some studies suggest that miR-204 is mainly expressed in insulinoma-regulating insulin secretion." (PMID 29922178, 2018). "GEP-NETs are usually asymptomatic until they metastasize, but tumor subtypes producing specific hormones such as insulin (termed insulinoma) and glucagon (termed glucagonoma) often present with hormone-associated symptoms during the localized stages of disease." (PMID 29590641, 2018). "Interestingly, DPP6 expression was also clearly present in the insulin positive cells from two separate human insulin producing tumors (insulinomas)." (PMID 29123178, 2017). "In two other studies, 5 μM of sodium arsenite (iAsIII) for 72 h in primary rat pancreatic β-cells reduced insulin mRNA expression and 0.5 μM sodium arsenite in a rat insulinoma cell line suppressed Ca2+ influx, thereby inhibiting insulin vesicle packaging and impairing GSIS." (PMID 28275977, 2017). "Notably, despite the widespread CpG abnormalities in this region, INS expression is preserved in insulinomas." (PMID 28974674, 2017). "Hypoglycemic episodes may be absent during the second half of pregnancy even in the presence of a confirmed insulinoma, but in the postpartum period they often recur after a rebound in insulin sensitivity." (PMID 28427440, 2017). "Therefore, to provide more reference parameters for the qualitative diagnosis of insulinoma, it is better to combine with the determination of the fasting blood glucose, the fasting insulin, the fasting C-peptide and the calculation of respective IRI." (PMID 28293303, 2017). "A direct implication of deoxySLs in the pathogenesis of T2DM was suggested by data from in-vitro studies, showing that deoxySLs inhibit glucose-stimulated insulin secretion and induce cell death in both the rat insulinoma cell line Ins-1 and primary rodent islets." (PMID 28472035, 2017). "Vasoactive intestinal peptide (VIP)/pituitary adenylate cyclase activating polypeptide (PACAP), and their receptors PAC1, VPAC1 and PAC2 have emerged as important factors in islet cell function (insulin secretion) and growth and differentiation of neuroendocrine tumors including insulinomas." (PMID 28496188, 2017). "Notably, insulin was consistently the most highly expressed transcript across all samples, confirming the identity of the PNETs as insulinomas." (PMID 28974674, 2017).
insulinoma (continued). "This behavior parallels the response of AdbPAC-transduced primary islets (see results in the next section) after photostimulation and is in support of a previous report indicating the resemblance in the regulation of insulin secretion between particular insulinoma lines and normal β-cells." (PMID 28839233, 2017). "Furthermore, higher concentrations of secreted PDZD2 in rat insulinoma cell lines were correlated with higher rates of cell proliferation and inhibited transcription of INS, an insulin promoter." (PMID 28007035, 2016). "Subsequently, we investigated whether 2-DG reduced insulin synthesis which had been increased by melatonin via EDC3 in rat insulinoma INS-1E cells." (PMID 27493704, 2016). "Interestingly, immunohistochemical staining for insulin was positive in only six of the nine patients with insulinoma in this study." (PMID 26911576, 2016). "Endogenous hyperinsulinemia could be related to insulinoma—the occurrence of neoplasm foci deriving from the pancreatic cells secreting insulin." (PMID 27526057, 2016). "We investigated whether 2-DG reduced intracellular insulin increased by melatonin via autophagy/EDC3 in insulinoma INS-1E cells." (PMID 27493704, 2016). "In order to find further proof for this hypothesis, we studied MAPT in a beta-cell derived rodent insulinoma Rin-5F cell line, which represents a model for the evaluation of mechanisms controlling transcription, storage, and secretion of insulin." (PMID 26824039, 2016). "We report that melatonin may directly regulate the intracellular biosynthesis of insulin in the presence of 2-DG in rat insulinoma INS-1E cells." (PMID 27493704, 2016). "Here, we examined that 2-DG or rapamycin-induced autophagy may decrease the production of intracellular insulin in INS-1E insulinoma cells." (PMID 27536716, 2016). "We investigated whether 2-DG reduced insulin synthesis which had been increased by melatonin via autophagy in rat insulinoma INS-1E cells." (PMID 27493704, 2016). "Our previous report showed that ER stress caused by melatonin, especially in the presence of thapsigargin, decreased intracellular insulin biosynthesis and that extracellular secretion of insulin may be regulated by melatonin in rat insulinoma INS-1E cells." (PMID 27493704, 2016). "Immunofluorescence staining of islets from prediabetic and diabetic mice revealed a disconnect between insulin and amylin protein expression and and were supported by an increase in amylin mRNA expression in human insulinomas following exposure to high dose streptozotocin." (PMID 27111653, 2016). "Using a human non islet cell insulinoma cell line (TC-YIK) which expresses insulin and the majority of known pancreatic beta cell specific genes as an example, we describe a general approach to identify key cell-type-specific transcription factors (TFs) and their direct and indirect targets." (PMID 26635867, 2015). "Although urinary and plasma C-peptide levels showed that insulin secretion was not depleted, anti-insulinoma-associated antigen 2 antibody was present." (PMID 25759758, 2015). "We also used INS-1E insulinoma cells, which secrete insulin in response to glucose." (PMID 26300732, 2015). "Insulin secretion from human and mouse pancreatic islets exposed to 20 mM glucose is pulsatile, and studies of mouse islets and insulinoma cells have demonstrated that secretory pulses are driven by synchronous oscillations of the cytoplasmic concentrations of Ca2+ and cAMP." (PMID 25911612, 2015). "Indeed silencing BAG3 in β-TC-6 mouse insulinoma cells results in reduced intracellular content of insulin and in its increased secretion in response to glucose stimulation." (PMID 25766323, 2015). "Insulinoma was diagnosed based on a fasting blood glucose level of 15 mg/dL, a high fasting immunoreactive insulin/blood glucose ratio (>0.3), and the presence of a tumor, 12 mm in diameter, that was detected in the pancreas head by abdominal computed tomography (CT)." (PMID 26107678, 2015).
insulinoma (continued). "Indeed using a mouse insulinoma β-TC-6 cell model here we show that BAG3 silencing affects F-actin polymerization state resulting in increased insulin secretion." (PMID 25766323, 2015). "In majority of insulinomas, a great deal amount of insulin is secreted by tumor cells." (PMID 25099181, 2014). "The major product of this pathway is pro-insulin and is released in large amounts in insulinomas." (PMID 25945127, 2014). "We speculate that high levels of insulin in patients with insulinomas might inhibit the secretion of CgA in these tumor cells." (PMID 25099181, 2014). "Murine insulinoma cell line MINI6 cultured in laminin 411 could increase the insulin gene expression significantly." (PMID 24885418, 2014). "Insulinoma is an uncommon insulin-secreting pancreatic islet cell neuroendocrine (NE) tumor." (PMID 25298880, 2014). "Insulinoma is a NEN arising from insulin-secreting cells in pancreatic islets." (PMID 25038902, 2014). "This test, even if not widely available, is diagnostic of insulinomas secreting immature forms of insulin." (PMID 25038902, 2014). "Moreover, octreotide hyperpolarizes insulinoma cells by activating (K-ATP) channel and thus lowers insulin secretion." (PMID 24932607, 2014). "Indeed, treatment of islets or insulinoma cells with LPS or with cytokines dramatically alters insulin secretion." (PMID 25383781, 2014). "It is generally considered that insulinoma may also be characterized by low blood glucose and high insulin levels." (PMID 25289063, 2014). "Insulinoma is a rare form of insulin-secreting pancreatic islet cell neuroendocrine (NE) tumor." (PMID 25298880, 2014). "Amolopin exhibited markedly insulin-releasing activity on rat insulinoma INS-1 cells." (PMID 25294221, 2014). "AFP I and III at concentrations of 10 mg/ml could keep alive approximately 60% of a insulinoma cell-line for 120 h, and the preserved cells retained the ability to secrete insulin." (PMID 24069217, 2013). "We evaluated GSIS in the insulin-secreting rat insulinoma cell line INS-1E." (PMID 23565276, 2013). "One possible mechanism is a C21-mediated decrease in TNF-α, since TNF-α is known to induce apoptotic cell death in mouse primary β cells and insulinoma cell lines, and inhibit glucose-stimulated insulin transcription and secretion observed in the HIT-T15 pancreatic β cell line." (PMID 23155382, 2012). "Indeed, 10 years ago, the GLP-1R was found to be expressed in insulin-producing islet cell tumors, i.e., insulinomas." (PMID 23230431, 2012). "Similarly, TGF-β1 and Activin A, another TGF-β family member, stimulate short-term (five minutes) insulin secretion in mouse insulinoma cells by increasing cytoplasmic Ca2+ concentration." (PMID 22359515, 2012). "We first confirmed the utility of this region to report insulin production by transfecting a phINS-EGFP construct into the HIT-T15 hamster insulinoma clonal cell line (insulin-producing), as well as the NT-2 human embryonic carcinoma cell line (non-insulin-producing)." (PMID 22530041, 2012). "For example, cocaine- and amphetamine-regulated transcript (Cart) is upregulated in our studies and was recently reported to be expressed in pancreatic β-islet cells and to enhance insulin secretion from an insulinoma cell line and from isolated rat islet cells." (PMID 21931641, 2011). "By 120 min, however, blood glucose levels in animals transplanted with pericentrin-depleted islets and insulinoma cells has returned to normal, suggesting that the glucose stimulated insulin biosynthesis and trafficking of granules to the membrane were not inhibited." (PMID 20676397, 2010). "However, similar to the islet transplanted mice, plasma insulin levels were higher in mice transplanted with pericentrin depleted insulinoma cells compared to control mice, although the increase was not statistically significant." (PMID 20676397, 2010).
insulinoma (continued). "This would seem to indicate that in the insulinoma cell line, either 3 mM glucose or 1 mM taurine could elicit insulin release as effectively as the other." (PMID 20804585, 2010). "Regulation of insulin secretion machinery and transcription factor Foxa2 in insulinoma cells." (PMID 20860821, 2010). "Moreover, in accordance with the described behaviour of insulinomas, decreased C-peptide release and barely detectable insulin content were also observed in these cultures." (PMID 19545371, 2009). "In this report, we highlight the utility of the rapid intraoperative insulin assay as an effective and unique method to confirm curative resection of insulinoma in the pediatric patient, a population where other hyperinsulin-producing conditions, such as nesidioblastosis, must be considered as well." (PMID 17958895, 2007). "It is not known whether the expression level of one or both subunits plays a role in the abnormal insulin secretion by canine insulinomas." (PMID 16266437, 2005). "In addition, laboratory markers such as insulin and c-peptide levels, as well as, imaging modalities such as CT scan or MRI, can also be used to exclude insulinoma, which is a focal disease process and therefore aid in the diagnosis of nesidioblastosis which is a diffuse disease process." (PMID 38817472, 2024). "Another possible condition is non-insulinoma pancreatogenous hypoglycemia syndrome, often seen after gastric bypass surgery, which involves hyperinsulinemic hypoglycemia due to islet cell hyperplasia, but typically it presents with elevated insulin levels postprandially." (PMID 39463547, 2024). "Thus, to evaluate whether the VFPE could modulate insulin secretion in beta cells, we performed an in vitro experiment using rat insulinoma INS-1E cells incubated with 5 or 10 mg/mL of the VFPE in a low or high glucose culture medium." (PMID 37175691, 2023). "It is even more difficult in pregnant women because hypoglycemic symptoms in the early stage of pregnancy may be mistaken for those of hyperemesis gravidarum, and insulinoma-related symptoms rarely occur after mid-pregnancy due to the enhancement of insulin resistance seen in pregnancy." (PMID 37563593, 2023). "The discrepancy between studies in human medicine and our study could be explained by the fact that, in studies of humans, insulin concentration was compared between cases of benign and malignant insulinomas whereas, in our study, all dogs had malignant neoplasia, albeit of different stages." (PMID 37194422, 2023). "Insulinoma in women during pregnancy and postpartum is very rare; approximately 65% of cases are diagnosed early in pregnancy and ~ 35% immediately after delivery, few being found in middle or late pregnancy, likely due to increased insulin resistance seen after early-stage pregnancy." (PMID 37563593, 2023). "We then assessed to what extent the elevated mitochondrial labile iron (mLI) and ROS (mROS) observed in NAF-1(−) insulinoma cells contributed to impaired stimulated insulin secretion, and whether alleviating mLI and mROS accumulation will improve glucose-stimulated insulin secretion." (PMID 34439408, 2021). "These latter observations suggest that NFaT transcription factors may respond to non-islet-specific signals that participate in modifying chromatin structure in the 11p15.5-p15.4 target sub-region, thereby affecting the expression pattern of the INS/IGF2 locus in insulinomas." (PMID 33060578, 2020). "However, it is not clear whether blood levels of acylated ghrelin are affected by higher circulating levels of insulin/proinsulin in patients with insulinoma." (PMID 32124259, 2020). "There may be increased production of insulin from insulinomas or islet cell hyperplasia." (PMID 29849273, 2018).